HLA-DQA1 (major histocompatibility complex, class II, DQ alpha 1)
Diseases named in the same sentence as HLA-DQA1 in open-access papers (continued):
Sharing a sentence is not in itself a finding about the gene and the disease.
type 1 diabetes (30 papers, 2006 to 2026). "It is known that HLA-DQA1*0505 is a protective gene for type 1 diabetes and breast cancer and is also a susceptibility factor for common variant immunodeficiency and chronic myeloid leukemia." (PMID 38725645, 2024). "We also confirmed the associations of rs9272785 (HLA-DQA1 gene) with type 1 diabetes and its manifestations with FDR significance across ancestries." (PMID 37196047, 2023). "The HLA-DQA1*05:01/DQB1*02:01 (DQ2.5) and HLA-DQA1*03:01/DQB1*03:02 (DQ8.1) alleles are positively associated with type 1 diabetes (T1D), while the HLA-DQA1*01:02/DQB1*06:02 (DQ6.2) allele is negatively associated with this disease." (PMID 36672249, 2023). "Taken together, our study identified the HLA-DQA1*03:03 allele in well-described HLA type 1 diabetes risk haplotypes and thus helps to correct current inconsistencies in type 1 diabetes risk haplotype nomenclature." (PMID 34946827, 2021). "Of particular note are signals rs9273410 and rs776111176 both corresponding to HLA-DQA1/A2/B1/B2 candidate genes, which had the widest disease associations including Hay fever, type 1 diabetes, inflammatory bowel disease, ulcerative colitis and psoriasis." (PMID 35386986, 2021). "This study identified the HLA-DQA1*03:03 allele as an addition to the already known type 1 diabetes risk haplotypes, and can contribute to more precise HLA genotyping approaches." (PMID 34946827, 2021). "HLA-DQA1 alleles were also very strongly associated with Type 1 diabetes in African Americans, reflecting the strong linkage disequilibrium with highly disease-associated HLA-DRB1 and HLA-DQB1 alleles." (PMID 23398374, 2013). "The HLA-DQA1*0102 allele is known to be a protective allele against type 1 diabetes mellitus (DM) and systemic lupus erythematosus, which are classical autoimmune diseases." (PMID 16879749, 2006). "However, previous studies have confirmed that HLA-DQA1 is a susceptibility gene for type 2 diabetes and type 1 diabetes." (PMID 39060963, 2024). "Both studies reported an African-specific HLA-DRB1*07- HLA-DQB1*02 haplotype that predisposed to Type 1 diabetes and carried the 03:01 allele at HLA-DQA1, which is associated with increased risk of Type 1 diabetes in Europeans, suggesting a causal role for HLA-DQA15." (PMID 23398374, 2013). "However, as reported by others 5,6, we observed that the effect of the HLA-DRB1*07:01 haplotype on Type 1 diabetes risk is dependent on the HLA-DQA1 allele present." (PMID 23398374, 2013). "Twin and family studies demonstrate that genetic factors contribute to ~50% of the risk of type 1 diabetes, with variation in HLA class I (HLA-A, HLA-B, HLA-C) and HLA class II (HLA-DRB1, HLA-DQA1, HLA-DQB1) accounting for 30%- 50% of genetic risk." (PMID 40832419, 2025). "HLA-DRB1*0801 and HLA-DQA1*0401 are in strong LD with HLA-DQB1*0402 (P = 5.2 × 10−8) and have been associated with autoimmune disease, including type 1 diabetes and systemic lupus erythematosus." (PMID 36929174, 2023). "Type 1 diabetes predisposing human leukocyte antigen (HLA) alleles (i.e., HLA-DRB1, HLA-DQA1, and HLA-DQB1) were found in 14.3% of subjects." (PMID 35010780, 2022). "The combination of HLA-DQA1*03:01 and DQB1*03:02 alleles (summarized as ‘HLA-DQ8′) is reported to be among the two most prevalent HLA class II haplotypes in Caucasian type 1 diabetes patients." (PMID 34946827, 2021). "Using the WTCCC type 1 diabetes data, we were able to accurately assess the risk of haplotypes spanning HLA-DRB1, HLA-DQA1 and HLA-DQB1." (PMID 23762245, 2013). "Twin and family studies have demonstrated that genetic factors contribute to approximately 50% of the risk for type 1 diabetes, with variations in HLA class I (HLA-A, HLA-B, HLA-C) and HLA class II (HLA-DRB1, HLA-DQA1, HLA-DQB1) accounting for 30–50% of the genetic risk." (PMID 41037100, 2026).
type 1 diabetes (continued). "Highly associated pathways such as KEGG "Type I Diabetes," "Antigen processing and presentation," and "Systemic lupus erythematosus" share several genes, particularly HLA class I and II paralogs (HLA-DRB1, HLA-DQB1, HLA-DQA1, HLA-B)." (PMID 39495786, 2024). "Against this background, we compared type 1 diabetes susceptibility between HLA-DQA1*03:01 or HLA-DQA1*03:03 carriers, and our results revealed no major differences in type 1 diabetes risk." (PMID 34946827, 2021). "In contrast, the effect size for HLA-DQB1*03:02 allele tagged by this SNP differs among the AFR (OR=1.68; the HLA-DQA1*03:01 allele is most strongly associated with type 1 diabetes risk, with effect OR=5.45), AMR (not significant in this group), EUR (OR=5.33) and FIN (OR=3.91) groups." (PMID 41037100, 2026). "In cluster 2, the significantly enriched genes were HLA-B, HLA-A, HLA-DRB1, HLA-DQA1 and HLA-DQB1, with all genes related to allograft rejection, GVHD, type I diabetes, autoimmune thyroid disease and viral myocarditis." (PMID 37063831, 2023).
autoimmune disease (18 papers, 2006 to 2025). A disorder resulting from loss of function or tissue destruction of an organ or multiple organs, arising from humoral or cellular immune responses of the individual to their own tissue constituents. "In the Finnish population, several HLA alleles have been reported to be associated with susceptibility to infectious diseases and autoimmune diseases, such as HLA-DQA1*03:01 and HLA-DQB1*03:02." (PMID 40300101, 2025). "The HLA-DQA1 gene has been previously associated with several autoimmune diseases, and is related to UC, RA, MS, and T1D in this study across many tissues." (PMID 39590325, 2024). "In hypothyroidism, recent studies have revealed that immune-related genetic variants, such as HLA-DQA1_rs17426593, are closely associated with disease occurrence, which is consistent with the primary cause of hypothyroidism- autoimmune disease (such as Hashimoto’s thyroiditis)." (PMID 41202080, 2025). "Interactions between HLA-DQA1 variants and other HLA genes have been linked to susceptibility to various autoimmune diseases, including rosacea, narcolepsy, idiopathic inflammatory myopathies, alopecia areata, juvenile idiopathic arthritis, and autoimmune Addison’s disease." (PMID 40806407, 2025). "Within this chromosome, HLA-DQA1, HLA-DRB6, HLA-DQA2, HLA-DQB2, HLA-DRB1, and HLA-DQB1-AS1 were notable for having causal associations among several autoimmune diseases." (PMID 39590325, 2024). "GSTT1 has been linked to breast cancer, NAFLD to non-alcoholic fatty liver disease, and HLA-DRB5 and HLA-DQA1 to autoimmune diseases." (PMID 23594316, 2013). "The precise mechanisms by which different allelic variants of the HLA-DQA1 gene contribute to autoimmune disease risk are not fully understood." (PMID 40806407, 2025). "Other immune diseases, such as RA (hsa05323) were associated with HLA-DQA1 and ATP6V1G2 locus and it was also revealed that autoimmune diseases may coexist with NMOSD or share common pathological pathways." (PMID 34367251, 2021). "It has been reported that specific allelic combinations of HLA-DQA1, HLA-DQB1, and HLA-DRB1 genes influence autoimmune disease predisposition, and, furthermore, their expression levels may also correlate with causes of the disease." (PMID 32547543, 2020). "Further analyses using imputed HLA allele frequencies indicated that especially HLA genes HLA-A, HLA-DRB1, HLA-DRB4, HLA-DQA1, and HLA-DQB1 may play a role in endodontic infections independent of autoimmune diseases." (PMID 40701953, 2025).
rheumatoid arthritis (17 papers, 2013 to 2025). A chronic, systemic autoimmune disorder characterized by inflammation in the synovial membranes and articular surfaces. "Rs9272785 (HLA-DQA1 gene) also marked the most significant association in EA PheWAS with ‘rheumatoid arthritis’." (PMID 37196047, 2023). "SNP rs9272785 (HLA-DQA1 gene, proxy variant for rs7990) generated the most significant association in MA PheWAS coupled with ‘rheumatoid arthritis’." (PMID 37196047, 2023). "For instance, several HLA-DRB1 alleles have been associated with susceptibility to rheumatoid arthritis (RA) in different populations, HLA-DQA1 and HLA-DQB1 alleles have been strongly associated with type-1 diabetes and celiac disease, and specific HLA-DRB3*03:01 allele with Crohn’s disease." (PMID 39835139, 2024). "For example, there are many drugs available, which may offer a starting point for targeting of the HLA-DQA1/B1 genes such as azathioprine, which is an immunosuppressant already in use to treat rheumatoid arthritis, Crohn's disease and ulcerative colitis." (PMID 35386986, 2021). "As with the original DMG-alone analysis, the MEGs were also significantly 3.75-fold enriched in the KEGG ‘Rheumatoid arthritis‘ pathway (q = 1.70E-02, where q is a multiple-test corrected P-value) with 7 out of 89 genes: ANGPT1, CSF2, CTLA4, HLA-DQA1, HLA-DQA2, HLA-DRA and HLA-DRB1." (PMID 25901943, 2015).
diabetes (15 papers, 2006 to 2025). "We demonstrated DR4DQ2+ haplotype is associated with early clinical onset of diabetes in comparison with other haplotypes, confirmed the reported results of a study carried out in Central Europe, where HLA-DQA1*03-DQB1*02 haplotype was identified more rarely but associated with early onset." (PMID 36409706, 2022). "Moreover, one diabetes associated SNP (rs9272346 HLA-DQA1, PT1D<10−128) was found through the proxy search to overlap with a cis-mQTL-SNP (rs1063355 HLA-DQB1, R2 = 0.87) that showed association with mRNA expression in the human islets." (PMID 25375650, 2014). "The HLA-DQA1*01:01 allele was found to be significantly associated with T1D, with frequencies of 98 in the patient group and 61 in the control group, suggesting that this allele may serve as a potential risk factor for diabetes." (PMID 40117003, 2025). "Similarly, specific HLA-DQA1 and HLA-DQB1 genes have been associated with susceptibility to type 2 diabetes mellitus (T2DM)." (PMID 40771282, 2025). "In our participants with diabetes, the HLA-DQA1-rs1048372 variant showed a significant and different direction of effect over serum TG levels, compared with participants without diabetes." (PMID 39258111, 2024). "For the rest of the genes with associations only in the cohort with diabetes (ZZEF1 and Chol, ATXN7, PC, HLA-DQA1 and HDL), this study is the first to identify an association and more research will be required to establish a comprehensive understanding of their impact." (PMID 39258111, 2024). "When we examined the T2DM group who did not develop nephropathy, despite many years of diabetes, we found decreased frequencies of the HLA-DQA1*0302 and HLA-DQB1*0501 alleles compared to the non-DN group." (PMID 23671871, 2013). "Also, a genome-wide analysis of the DNA methylation quantitative trait locus (mQTL) in human pancreatic islets revealed 383 CpGs (0.08% of tested CpGsites), showing significant associations including known diabetes loci, e.g., ADCY5, KCNJ11, HLA-DQA1, INS, PDX1 and GRB10." (PMID 38136971, 2023). "Subgroup analysis comparing the cohorts homozygous for both the high-risk alleles for HLA-DQA1 and PLA2R1 (TT and AA respectively) with those not homozygous for both show a similar proportion of diabetes, both self-reported and through HES linkage." (PMID 37104302, 2023).
breast carcinoma (14 papers, 2013 to 2025). "The results of the present study suggested that low HLA-DQA1 expression was associated with poor prognosis in breast cancer patients." (PMID 37434241, 2023). "In accordance with our results, low HLA-DQA1 expression was associated with poor prognosis in hepatocellular carcinoma, lung cancer, breast cancer, and soft tissue sarcoma; its reduction indicated the presence of an immunosuppressive microenvironment and invasive disease." (PMID 40867248, 2025). "In oral cancer and breast cancer, HLA-DQA1 polymorphism is related to incidence, and high levels of expression are associated with better prognosis, offering potential biomarkers for prediction and treatment of oral cancer and breast cancer." (PMID 37884883, 2023). "In addition, the HLA-DQA1 gene predicts hepatotoxicity risk in breast cancer treated with epidermal growth factor receptor (EGFR) inhibitors." (PMID 37434241, 2023). "However, the association between HLA-DQA1 expression and prognosis of breast cancer and the noninvasive assessment of HLA-DQA1 expression are still unclear." (PMID 37434241, 2023). "Also, the HLA-DQA1-02:01 allele shows a direct association with the development of hepatotoxicity in patients with breast cancer receiving lapatinib over the treatment protocol." (PMID 38156855, 2023). "In conclusion, the present study indicated that high HLA-DQA1 expression is associated with a better prognosis in breast cancer patients and the differentially expressed genes are enriched in the OXPHOS, estrogen response early and estrogen response late signalling pathways." (PMID 37434241, 2023). "High HLA-DQA1 expression is associated with a better prognosis in breast cancer." (PMID 37434241, 2023). "Also, Iran authors found a negative association between the alleles, HLA-DRB1*1301 and HLA-DRB1*0101, and breast cancer, while they found positive associations between the allele HLA-DQA1*0301 and this cancer." (PMID 34712820, 2021). "Unlike previous studies, this study was not limited to single molecular typing of breast cancer and used a different approach radiomics to predict HLA-DQA1 expression." (PMID 37434241, 2023). "This study aimed to reveal the association and investigate the potential of radiomics to predict HLA-DQA1 expression in breast cancer." (PMID 37434241, 2023). "In the present study, the relationship between HLA-DQA1 expression and breast cancer prognosis was explored, and then the potential molecular mechanisms of different HLA-DQA1 expression groups were analysed." (PMID 37434241, 2023). "HLA-DQA1 and HLA-G polymorphisms reshape antigen presentation and the tumor microenvironment, while CTSW rs3903072 is associated with greater tumor-infiltrating lymphocyte activity in breast cancer." (PMID 41244914, 2025). "Finally, a radiomics model that can predict HLA-DQA1 expression was established as a new practical imaging biomarker for breast cancer prognosis." (PMID 37434241, 2023). "On the other hand, some researchers found a significant lack of association between breast cancer and HLA-DQA1 in southern Taiwanese women." (PMID 33976942, 2021). "Two SNPs (SALL1 rs10521222 and HLA-DQA1 rs9271608) and lifestyles, including alcohol intake, lifetime cumulative exposure to estrogen, and overall and visceral obesity, are the most common and strongest predictive markers for breast cancer across the analyses." (PMID 33441805, 2021). "However, the ability of radiomics to assess the expression of HLA-DQA1 in breast cancer is unclear." (PMID 37434241, 2023). "Our study is the first to report the association of the HLA-DQA1 SNP with breast cancer risk in non-Hispanic white women, suggesting that HLA class II plays a decisive role in the pathogenesis of breast cancer in this population by diminishing the efficacy of the antitumoral immune response." (PMID 33441805, 2021).
breast carcinoma (continued). "HLA-DQA1 belongs to the alpha chain of human major histocompatibility complex class II (MHC-II) and plays a decisive role in the pathogenesis of breast cancer." (PMID 37434241, 2023). "Both measures with high ranks indicated 5 SNPs (SALL1 rs10521222; HLA-DQA1 rs9271608; DUSP1 rs17658229; APOC1 rs4420638; and TRAIP rs2352975) and 3 lifestyles (duration of OC and E + P use and BMI) as the most influential variables for breast cancer." (PMID 33441805, 2021).
COVID-19 (14 papers, 2020 to 2025). A disease caused by infection with severe acute respiratory syndrome coronavirus 2. "HLA-DQA1 gene, which encodes the HLA class II histocompatibility antigen, DQ alpha 1 chain, appears also to be down-regulated in severe COVID-19 patients." (PMID 37347079, 2023). "The identification of HLA-SH markedly improved the risk assessment compared to the conventional genotyping, since the differential risk of severe forms of COVID-19 was increased up to 5-fold between males and females, as in the case of HLA-SH#1 of the HLA-DQA1 gene that is of high risk in females." (PMID 39684907, 2024). "In contrast, expression of MHC-II genes (HLA-DQB1, HLA-DPB1 and HLA-DQA1, etc.)were decreased in COVID-19 acute necrotizing encephalopathy patients, indicating an immune paralysis of T cells." (PMID 37848421, 2023). "Subpopulations of Mono_FCGR3A (CD16 monocytes expressing FCGR3A), Mono_HLA-DPB1, and Mono_HLA-DQA1 were depleted in patients with COVID-19-induced ARDS." (PMID 37363730, 2023). "Consistently, DCs from COVID-19 patients also displayed lower antigen presentation capacity than healthy donors, with genes associated with antigen presentation (e.g., HLA-DQB1, HLA-DEB5 and HLA-DQA1, etc.)downregulated in DCs from the COVID-19 groups including those with encephalopathy." (PMID 37848421, 2023). "Nasal macrophages had several differentially expressed (DE) genes in patients with COVID-19 versus patients with LRTD that mirrored alveolar macrophage responses (SPP1, LGALS1 and TMSB10), including IFN-γ response genes (HLA-DPB1, HLA-DQA1 and C1QB)." (PMID 39567718, 2024). "A recent large-scale WGS association study identified a significant association between the lead SNP rs9271609, located upstream of HLA-DQA1 and HLA-DRB1 in the HLA class II region, and COVID-19 severity." (PMID 38181733, 2024). "Our analysis revealed a downregulation of FXYD, HLA-DRB1, and RPS20 in memory B cells; MTATP8 and HLA-DQA1 in naïve cells; RPS4Y1 in activated B cells; and IGHV3-73 in plasma cells in COVID-19 patients." (PMID 36826040, 2023). "In particular, the naïve cells of COVID-19-infected subjects showed downregulation of MT-ATP8 and HLA-DQA1." (PMID 36826040, 2023). "In contrast, genes involved in antigen presentation through MHC II presented a “valley” pattern, with under-expression among TUBE early compared to HLTY and COVID-19 compared to INFL, which strikingly predominated in TUBE early (e.g. HLA-DRA, HLA-DRB1, HLA-DQA1, CD74/Ii/CLIP/SLIP)." (PMID 34135895, 2021). "Regarding the downregulated geneset, MHC II molecules, including HLA-DQA1, HLD-DRA, HLA-DRB1, HLA-DMB, HLA-DMA, etc., and cytokine/chemokine genes, including IL1B, TNF, CCL3, CCL4, and CXCL8 were expressed at lower levels in COVID-19 patients, especially those with severe diseases." (PMID 33101705, 2020).